IL1B (interleukin 1 beta)
Diseases named in the same sentence as IL1B in open-access papers (continued):
Sharing a sentence is not in itself a finding about the gene and the disease.
ulcerative colitis (continued). "Oat beta-glucan has also been previously shown to decrease the mRNA and protein expression of pro-inflammatory cytokines such as IL-1β, IL-6, and TNF-α in mice suffering from dextran sulfate sodium (DSS)-induced ulcerative colitis." (PMID 32707913, 2020). "It is well known that ulcerative colitis is characterized by the production of a wide range of inflammatory cytokines, including TNF-α, IL-1β, and IL-6." (PMID 31827675, 2019). "In a mouse model of ulcerative colitis, which was induced by dextran sulfate sodium, expressions of TNF-α, IL-1β, and IL-6 were markedly up-regulated in the colon, resulting in intestinal mucosal inflammation." (PMID 29694505, 2018). "Since DSS induced ulcerative colitis, the expressions of three proinflammatory cytokines (TNF-α, IL-6, and IL-1β) were examined in the serum and colorectum tissue." (PMID 29483924, 2018). "We found that the patients suffered ulcerative colitis had high serum SDC1 levels,presented with increased levels of P65, tumour necrosis factor alpha (TNF‐α) and IL‐1β and higher circulating neutrophils." (PMID 27558380, 2017). "Specifically, increased levels of TNF-α, IL-1β, IFN-γ, IL-6, and IL-8 have been reported in ulcerative colitis patients." (PMID 23630633, 2013). "Recently, we reported that production of pro-inflammatory cytokines, IL-1β, IL-6, and TNF-α, was significantly decreased by oral administration of L. plantarum K68 in DSS-induced ulcerative colitis mice." (PMID 23690866, 2013). "Relative studies found that in vivo administration of ferulic acid alleviated intestinal damage in ulcerative colitis (UC) rats and suppressed the expression of inflammatory factors TNF-α, IL-12, and IL-1β, indicating that ferulic acid possesses significant anti-inflammatory activity." (PMID 40428394, 2025). "Inflammatory cytokines play crucial roles in the development of ulcerative colitis, as shown in DSS-treated mice, which presented significantly increased levels of inflammatory cytokines, including IL-1β, IL-23, and IL-17F, in colon extracts, whereas TNF-α levels were elevated in the serum." (PMID 40576745, 2025). "In conditions such as Crohn’s disease, ulcerative colitis, renal disease, as well as infections with pathogens NLRP3 and its downstream cytokine IL-1β are essential for preserving intestinal epithelial structure, promoting barrier repair, and ensuring tissue homeostasis." (PMID 41394833, 2025). "Studies indicate that they may be beneficial in treating ulcerative colitis (UC) by modulating intestinal immunity and reducing proinflammatory cytokines such as TNF-α and IL-1β while increasing anti-inflammatory factors like IL-10." (PMID 40077619, 2025). "Interestingly, APOE, C1QB, and matrix metalloproteinase 12 (MMP12) are highly expressed in C1QB+ macrophages, IL-1B+ macrophages and CALD1+ macrophages from ulcerative colitis patients." (PMID 39095853, 2024). "Zhao Tian-yu reported that a Phellinus igniarius polysaccharide (A3) with an α-1, 6-D-GALp structure could significantly reduce IL-6, IL-1β, and TNF-α mRNA expression in RAW264.7 cells and mice with LPS-induced ulcerative colitis." (PMID 39202931, 2024). "One study reported the use of mucosal proinflammatory gene signatures (TNF, interleukin 1 alpha [IL1A], regenerating family member 1 alpha [REG1A], IL8, interleukin 1 beta [IL1B], and leukocyte immunoglobulin-like receptors A [LILRA]) in patients with ulcerative colitis." (PMID 39483464, 2024). "Moreover, we also portrayed 5 subpopulations of monocytes, C1QB+ macrophages, CALD1+ macrophages, IL-1B+ macrophages, and SERPINA1+ macrophages in the intestinal mucosa from ulcerative colitis patients." (PMID 39095853, 2024). "Oral administration of C. bovis was also found to alleviate the inflammatory damage in the colon tissue of mice ulcerative colitis model induced by dextran sulfate sodium, accompanied by reduced levels of myeloperoxidase, SOD, and mRNA expression of IL-1β, IL-6, and TNF-α." (PMID 36903252, 2023).
ulcerative colitis (continued). "IL-1β is one of the factors enhancing the synthesis of PTX3; therefore its elevated expression in NETs may result in upregulation of PTX3 during ulcerative colitis." (PMID 37892129, 2023). "The present study found that APH reduced the inflammatory response by upregulating the content of IL-10 and downregulating the content of TNF-α, IL-1β, and IL-6, which demonstrates that APH could alleviate ulcerative colitis." (PMID 36359970, 2022). "In addition, using an ulcerative colitis mice model, GA reduced IL-6 and IL-1β, regulating the phosphorylation of NF-κB and IkB-α, and the expression of COX-2 and PGE2 in an ulcerative colitis model." (PMID 35456938, 2022). "Decreases IL-1β, TNF-α, MDA, MPO, NF-κB p65, TRAF6, LC3, Beclin1, p62 levels and cell apoptosis; increases SOD activity; and exerts obvious therapeutic effect on rat ulcerative colitis." (PMID 35566359, 2022). "Moreover, hydroxytyrosol was able to reduce NLRP3 inflammasome expression, and thus suppressed the expression of IL-18, IL-1β, and caspase-1 in DSS-induced ulcerative colitis." (PMID 35990343, 2022). "Moreover, it inhibited TNF-α, IL-1β, IL-12 IL-17A, and interferon-γ (IFN-γ) contents that were elevated due to ulcerative colitis." (PMID 36079895, 2022). "NLRP3 inflammasome is responsible for increased production of IL-1β, and suppressing NLRP3 inflammasome activation by inhibiting MKP1/NF-κB pathway could attenuate DSS-induced ulcerative colitis." (PMID 36339623, 2022). "In a mice model of ulcerative colitis, polydatin targets the NF-κB-p65 pathway and exerts an anti-inflammatory effect by blocking the expression of the main inflammatory cytokines TNF-α, IL-6, and IL-1β." (PMID 34887932, 2021). "In addition, in people suffering from ulcerative colitis, the levels of TNF-α, IL-6, and IL-1β are greatly increased in the mucosa and serum." (PMID 33204254, 2020). "By attracting additional immune cells, as well as inducing proinflammatory IL-1β release from immune cells, CCL20 may protract the inflammatory response in ulcerative colitis." (PMID 30347808, 2018). "IL-1β stimulates the production of the pro-inflammatory cytokine IL-6 which has been described to be up-regulated in mouse model of IBD and in human ulcerative colitis or Crohn’s disease patients." (PMID 23198878, 2012). "Since IL-1β, IL-6 and TL1A are all capable of inducing IL-22 production, it is possible that pathway redundancy and IL-23-independent induction of IL-22 might contribute to ustekinumab resistance in ulcerative colitis." (PMID 36192482, 2022). "Induction of MMP-1 by IL-1β or TNF was completely abolished by imipramine in all the investigated primary fibroblasts, including three different sets from healthy control (CO I, CO II, CO III) and three sets from patients with ulcerative colitis (UC I, UC II, UC III)." (PMID 19787068, 2009). "It was suggested that olsalazine has a therapeutic effect on ulcerative colitis induced by DSS in mice, and the mechanism may be related to the increase of IL-2, IL-10, IL-22, TGF, and EGF and the decrease of the expression of IL-7, IL-17, TNF-α, IL-1β, and IFN-γ." (PMID 37610966, 2023). "Similarly, aberrant regulation of IL-1α and IL-1β is a contributing mechanism in persistent inflammation in IBD, while alterations in the expression of genes involved in fatty acid metabolism may contribute to the pathophysiology of ulcerative colitis." (PMID 23382912, 2013). "Moreover, the ability of MCC950 to suppress both translational and transcriptional IL-1β and IL-18 of canonical and noncanonical NLRP3 inflammasome in the colon may be promising in inflammatory intestinal diseases other than ulcerative colitis." (PMID 29872077, 2018).
colorectal cancer (154 papers, 1998 to 2026). A primary or metastatic malignant neoplasm that affects the colon or rectum. "In colorectal cancer, the tumor microenvironment is deeply involved in both the initiation and advancement of the disease, with interleukin-1β (IL-1β) serving as a key mediator in several associated processes." (PMID 41267807, 2025). "Patients with colorectal cancer often have elevated levels of IL-1β, IL-6, and TNF-α, which are associated with aggressive tumor behavior and a poor prognosis." (PMID 41463421, 2025). "Similar results have been reported in colorectal cancer, where the higher expression of IL-1β was associated with better OS and RFS, indicating a beneficial, prognostic role in rectal cancer." (PMID 38397123, 2024). "A single nucleotide polymorphism study on IDB patients showed that a mutant of IL-1β increased the proportion of IBD-associated colorectal cancer in the population." (PMID 35662946, 2022). "Based on the differentially expressed genes (DEGs), expression levels of IL-1β and IL-11, genes encoding for cytokines in the tumor microenvironment that promote colorectal cancer progression, were decreased by GLSF." (PMID 35692861, 2021). "In cervical, gastric, and colorectal cancers, high IL-1B expression has been associated with shorter patient survival." (PMID 34837692, 2021). "A7450 T1 M1 cells secreted cytokines associated with favorable prognosis at least in colorectal cancer (such as GM-CSF, IL-1b), with known ability to enhance NK cell activity and foster Th1 cell development." (PMID 33087163, 2020). "The associations between IL-1B gene polymorphisms and clinical characteristics of colorectal cancer." (PMID 30563955, 2018). "The -31 T/C polymorphism of this gene is associated with colorectal cancer risk, as IL-1B-511 heterozygotes and T carriers has reduced risk of colorectal carcinoma development and it is associated with the recurrence of CRC." (PMID 26208990, 2015). "In any case, screening for carriers of IL-6 gene variants with high susceptibility to transcriptional dysregulation by IL-1β should be considered for identification of individuals with high-risk for therapy-resistant colorectal cancer." (PMID 18205904, 2008). "On the one hand, they can significantly inhibit NF-κ B/p65 signaling pathway activity, thereby down-regulating IL-6, TNF-α and IL-1β and up-regulating IL-10 in the serum of patients with colorectal cancer, which further reduces the inflammatory response associated with colorectal cancer." (PMID 40520902, 2025). "which suggested that IL1B+ Macrophage may be implicated in the oncogenic and therapeutic resistance in colorectal cancer." (PMID 39170612, 2024). "Therefore, before considering IL1B as a potential method to treat colorectal cancer, it is important to further examine the correlations between IL1B polymorphism and prognosis." (PMID 37894904, 2023). "Stratified analyses between IL-1B gene polymorphisms and risk of colorectal cancer." (PMID 30563955, 2018). "Genotype frequencies of IL-1B gene polymorphisms in colorectal cancer cases and controls." (PMID 30563955, 2018). "The association of genetic risk score of IL-1B with risk of colorectal cancer." (PMID 30563955, 2018). "Additional studies have reported that inflammatory markers such as IL-1β, IL-6, and TNF-α are strongly associated with F. nucleatum infection and are more highly expressed in colorectal cancers harboring this bacterium." (PMID 41267807, 2025). "Lipopolysaccharide has been shown to increase the PKM2 expression and STAT3 promoter binding, leading to TNF-α and IL-1β production in colorectal cancer." (PMID 40982322, 2025). "Alu RNA induces epithelial-to-mesenchymal transition in colorectal cancer via NLRP3 inflammasome activation and IL-1β release, while BC200 promotes EBV-associated nasopharyngeal carcinoma by sequestering miR-6834-5p to upregulate thymidylate synthase." (PMID 40565315, 2025).
colorectal cancer (continued). "It is well-established nowadays that patients with colorectal cancer have high levels of circulating cytokines, such as IL-1β, responsible, in turn, for fostering the invasiveness of CRC." (PMID 40869063, 2025). "Survival analysis of core genes suggests that high expression of IFNG, MMP9, and IL1B indicates a shorter survival time in colorectal cancer patients." (PMID 40868987, 2025). "A newly proposed framework—the complement/neutrophil/IL-1β–myeloid cell/IL-17A axis—further clarifies the involvement of the complement system in colorectal cancer progression." (PMID 41267807, 2025). "Wei et al17 found a similar increase in blood levels of TNF-α, IL-1β, and IL-6 in a rat model of colorectal cancer." (PMID 40241344, 2025). "Here, we showed that Alu RNA can induce epithelial-to-mesenchymal transition (EMT) through NLRP3 inflammasome activation and IL-1β release in colorectal cancer (CRC) cells." (PMID 38486106, 2024). "Colorectal cancer metastasis to the liver is primarily mediated by bacteria dissemination from the primary site, recruiting neutrophils via cytokines such as IL1-β, CCL2, TNFα, and IL6, ultimately forming a pre-metastatic niche." (PMID 38474175, 2024). "While IL-18, another member of the IL-1 family of cytokines, is dramatically lowered in CRC patients, IL-1α and IL-1β are significantly elevated, indicating a significant anti-tumourigenic effect in colorectal cancer." (PMID 38339377, 2024). "The plasma levels of several cytokines (interleukin-1β /IL-1β/, IL-2, IL-4, IL-10, IL-12, IL-15, TGFβ and IFNγ) of 20 patients with colorectal cancer and 21 healthy individuals were determined by ELISA." (PMID 39456247, 2024). "Increased expression of IL‐1β and TNF‐α was also implicated in colorectal cancer development and progression." (PMID 37341064, 2023). "For instance, through activation of NF-κB signaling pathway, PKM2 is critical for the production of TNF-α and IL-1β in colorectal cancer." (PMID 36797689, 2023). "Previous studies have reported elevated levels of several circulating cytokines in colorectal cancer patients, including IL-1β, IL-8, and TNF-α, which are thought to promote tumor development in the context of chronic inflammation." (PMID 37063892, 2023). "5,7-DMC suppresses the production of IL-1β, TNFα and IL-8 in the colorectal carcinoma HT-29 cell line." (PMID 37920212, 2023). "In our previous study, increased production of irradiated macrophage-derived IL-1β also lowered the survival of CT26 colorectal cancer cell-bearing mice." (PMID 36430236, 2022). "IL-1 and IL-1β signaling in neutrophils enhances the antimicrobial activities in colorectal cancer, which inhibits bacterial-driven inflammation and alleviated tumorigenesis." (PMID 36324574, 2022). "For example, serum TNF‐α, IL‐1β, IL‐6, and IL‐8 are positively associated with elevated HADS score in colorectal cancer patients." (PMID 34697903, 2022). "Inflammasomes in macrophages are activated by the macrophage-colorectal cancer cell crosstalk, then increasing IL-1β secretion and promoting colorectal cell migration." (PMID 35739593, 2022). "On the other hand, knockdown of human miR-375 upregulates NF-κB and pro-inflammatory factors, such as tumor necrosis factor-α, IL-1β, IL-6 and IL-8, in the colorectal cancer cell line Caco-2." (PMID 35052815, 2022). "We previously reported that ionizing radiation (IR) increases the production of interleukin (IL)-1β in lipopolysaccharide (LPS)-treated macrophages, contributing to the malignancy of colorectal cancer cells; however, the mechanism remained unclear." (PMID 36430236, 2022). "Dimethyl itaconate (DI) has been reported to be active against colorectal cancer via reducing the secretion of IL-1β from intestinal epithelial cells." (PMID 35095533, 2021).
colorectal cancer (continued). "Based on GSE136682 data, we found that IL-1β and IL-6 were increased in the intestinal tumor of mice after gavage administration by feces from colorectal cancer patients compared to their counterparts of mice fed by feces from healthy people." (PMID 34863291, 2021). "In our work, IL-1β and IL-6 were increased in the intestinal tumors of mice after being fed by feces from colorectal cancer patients compared to counterparts fed by feces from healthy people." (PMID 34863291, 2021). "IL-1α and IL-1β in the tumor microenvironment play critical roles in colorectal cancer growth by inducing tumor-elicited inflammation through IL-17A and IL-22 production in T cells." (PMID 33406733, 2021). "For instance, IL-1β, and IL-6 are highly expressed in colorectal cancer and infiltrating IL-1β receptor/IL-6 producing cells are increased in the stroma, which stimulates tumor cell growth." (PMID 33406733, 2021). "The cytokines IL-1β and TNF-α are strongly associated with inflammation-driven cancers, including colorectal cancer, and contribute to tumor growth and invasion." (PMID 34361836, 2021). "Dimethyl itaconate (DI) has been reported to be efficacious in colorectal cancer by decreasing IL-1β release from intestinal epithelial cells." (PMID 35095533, 2021). "Here, we explore how cancer cell-derived IL1β induces paracrine signaling in fibroblasts that causes resistance to oxaliplatin (L-OHP; a DNA inter and intra-strand cross link inducer) in colorectal cancer cell lines." (PMID 34066976, 2021). "Patients who suffer from colorectal cancer exhibit high serum levels of inflammatory mediators such as IL-1β, IL-6, TNF-α and PGE227,28." (PMID 31511625, 2019). "Angiogenesis in various tumors such as colorectal cancer is mediated by different molecules such as IL-1β, bFGF, VEGF, MMPs, and TNFα." (PMID 30127820, 2018). "We genotyped four polymorphisms in four genes (IL1B, TNF, PPARG, and PPARGC1A) and calculated the dietary inflammatory index (DII) in a case-control study with 701 colorectal cancer patients and 1,402 controls." (PMID 28051997, 2017). "The correlations of pretreatment serum concentrations of proinflammatory cytokines such as interleukin (IL)‐1β, IL‐6, and tumor necrosis factor‐α (TNFα) with the clinicopathologic features and progression of colorectal cancer (CRC) were investigated." (PMID 26799163, 2016). "IL-1B is involved in the survival and proliferation of remnant cancer cells after tumor resection in colorectal carcinoma." (PMID 26208990, 2015). "Pharmacological inhibition of IL-1β release from macrophages by vitamin D3, a potent chemopreventive agent for colorectal cancer, restored the ability of TRAIL to induce apoptosis of tumor cells cultured with macrophages." (PMID 20661477, 2010). "More recently, TNFα, Hepatocyte Growth Factor, PDGF and FGF19 and IL-1β have been shown to activate Wnt/β-catenin signaling, the oncogenic pathway activated in the majority of colorectal cancers." (PMID 20661477, 2010). "IL-1β and IL-6 are important cytokines for both intestinal inflammation and colorectal cancer." (PMID 40002819, 2025). "Interestingly, NLRP3-produced IL-1β induces the migration of colorectal cancer cells, and its activation in liver macrophages (Kupfer cells) decreases the metastasis of colorectal cancer cells." (PMID 40141358, 2025). "Additionally, a study indicated that patients with colorectal cancer exhibited higher levels of IL1B compared to healthy controls, and individuals with the CC genotype demonstrated elevated mRNA levels compared to those with the GG genotype." (PMID 40331958, 2025). "NLRC4-deficient mice with NAFLD also showed decreased tumor-associated macrophages (TAMs) and reduced IL-1β and VEGF expression, highlighting NLRC4’s role in managing the growth and recurrence of liver metastases in the context of both NAFLD and colorectal cancer." (PMID 39456655, 2024).